MAP3K7 (mitogen-activated protein kinase kinase kinase 7)
Diseases named in the same sentence as MAP3K7 in open-access papers (continued):
Sharing a sentence is not in itself a finding about the gene and the disease.
infection (7 papers, 2017 to 2025). The state of being infected such as from the introduction of a foreign agent such as serum, vaccine, antigenic substance or organism. "Following electroceutical treatment, anti-infection genes such as Il10ra and Foxp3 were up-regulated, whereas genes promoting immune response and metabolism, including Il17d and Map3k7, were down-regulated." (PMID 39951521, 2025). "Altered splicing of inflammatory and immune genes (e.g., IRAK4, MAP3K7, and CASP8) due to spliceosome mutations may contribute to MDS pathogenesis by leading to inflammation, changes in immune cell function, and increased risk of infection." (PMID 34196950, 2022). "In addition, MAP3K7 expression in infection patients was higher than that of control." (PMID 32214905, 2020). "In 3D4/21 cells, with increasing NS5A infection time, the protein expression of AKT1, IKBKG, CDC37, MAP3K2, and PKN2 decreased, whereas the protein expression of KRAS2 and MAP3K7 increased." (PMID 40078537, 2025). "The results revealed that with increasing infection time, the expression of IKBKG, AKT1, CDC37, MAP3K2, and PKN2 decreased, whereas the expression of MAP3K7 and KRAS2 increased." (PMID 40078537, 2025). "With increasing infection time, the expression levels of IKBKG and KRAS2 increased, whereas the expression levels of MAP3K7, MAP3K2, AKT1, CDC37, and PKN2 decreased." (PMID 40078537, 2025).
bacterial infections (1 paper, 2025). "The rewiring of MAPK signaling and activation of MAP3K7/TAK1 kinase has been associated with the induction of macrophage function in response to bacterial infections." (PMID 40150341, 2025).
cardiovascular disease (1 paper, 2015). "Findings related to cardiovascular disease and inflammation (MAP3K7 and SPSB1) could be tied to fenofibrate response, other findings are more difficult to link to the drug's mechanism (e.g., AGO1)." (PMID 26483836, 2015).
gynecologic tumor (1 paper, 2022). "Some of the differential NRGs are unique to a particular gynecologic tumor, such as BCL2L11 and OTULIN in CESC, MAP3K7 in OV, TLR2 in UCS." (PMID 36357839, 2022).
MAP3K7 also shares sentences with these, for which no sentence is quoted: gastric cancer (3 papers); Insulin resistance (3); Hepatic fibrosis (2); Hepatic steatosis (2); influenza (2); neurodegenerative disease (2); scrub typhus (2); age-related macular degeneration (1); Alzheimer disease (1); autoimmune pancreatitis (1); bladder cancer (1); breast tumor (1); Burkitt lymphoma (1); cardiofaciocutaneous syndrome (1); depression (1); developmental delays (1); Epstein-Barr virus infection (1); esophageal squamous cell carcinoma (1); gastroenteritis (1); genetic diseases (1); glioblastoma (1); glucose metabolic disorder (1); Hepatitis (1); herpes simplex infection (1); HIV-1 infection (1); infectious disease (1); inflammatory bowel disease (1); kidney disease (1); leiomyoma (1); liver cancer (1).
A further 17 diseases each share a sentence with MAP3K7 in 1 paper.